MAL2 (mal, T cell differentiation protein 2)
Description:
Member of the machinery of polarized transport. Required for the indirect transcytotic route at the step of the egress of the transcytosing cargo from perinuclear endosomes in order for it to travel to the apical surface via a raft-dependent pathway.
Tractability: Antibody: UniProt places it where antibodies can reach, with medium confidence; UniProt predicts a signal peptide or a membrane-spanning region; its Gene Ontology location is reachable by antibodies, with medium confidence. PROTAC: its protein half-life has been measured.
Gene: Protein-coding gene on chromosome 8 (119,165,034 to 119,249,903, forward strand). Ensembl gene ENSG00000147676.
Subcellular location: Cell membrane; Apical cell membrane; Endomembrane system; Cytoplasm, perinuclear region
Gene Ontology:
Molecular function: protein binding; structural constituent of myelin sheath
Biological process: myelination
Cellular component: extracellular exosome; membrane raft; membrane; apical plasma membrane; endomembrane system; perinuclear region of cytoplasm; plasma membrane
Genetic constraint (gnomAD): Loss-of-function variants: 17 observed, 15.85 expected, observed/expected ratio (o/e) 1.07, 90% interval 0.73 to 1.6. The upper end of that interval is the gene's LOEUF score, 1.6, which puts it in group 6 of 6, group 1 being the genes least tolerant of losing a copy. Missense variants: 222 observed, 194.98 expected, observed/expected ratio (o/e) 1.14, 90% interval 1.02 to 1.27. Synonymous variants: 102 observed, 84.33 expected, observed/expected ratio (o/e) 1.21, 90% interval 1.03 to 1.43.
Homologues: Orthologues: chimpanzee MAL2 (99% identical), dog MAL2 (93% identical), mouse Mal2 (91% identical), pig MAL2 (90% identical), rabbit MAL2 (89% identical), macaque MAL2 (81% identical), rat Mal2 (80% identical), tropical clawed frog mal2 (55% identical), zebrafish mal2 (55% identical), guinea pig MAL2 (52% identical), Caenorhabditis elegans F28H1.4 (26% identical), Caenorhabditis elegans F47B3.3 (19% identical). Paralogues in human: MAL (34% identical), MALL (32% identical), CMTM8 (22% identical), PLLP (20% identical), CMTM4 (19% identical), CMTM6 (15% identical), MARVELD1 (15% identical), CMTM3 (15% identical), CMTM7 (14% identical), PLP2 (12% identical), CMTM5 (11% identical), CMTM2 (10% identical), and 2 more.
Diseases named in the same sentence as MAL2 in open-access papers:
MAL2 is named in the same sentence as 70 diseases in open-access papers, as found by Europe PMC text mining. Sharing a sentence is not in itself a finding about the gene and the disease. The quoted sentences say what the papers report.
breast carcinoma (26 papers, 2009 to 2026). "MAL2 exhibits high expression levels in diverse cancers and is closely linked to cancer development and prognosis, such as breast cancer, ovarian cancer and pancreatic cancer." (PMID 37958451, 2023). "In fact, MAL2 was the fourth highest HPA-ranked gene with the highest significance associated with an unfavorable prognosis in breast cancer." (PMID 37345137, 2023). "We bioinformatically identified two novel super-enhancer-associated genes – NSMCE2 and MAL2 – highly upregulated in breast tumors, for which high RNA levels significantly and specifically correlate with breast cancer patients’ poor prognosis." (PMID 36224576, 2022). "In summary, pharmacological blockade of SEs confirmed NSMCE2 and MAL2 are associated with SEs in breast cancer cells." (PMID 36224576, 2022). "Breast cancer patients with high MAL2 expression were associated with worse overall survival (P=0.00093)." (PMID 34567213, 2021). "To identify the biological function of MAL2 in breast cancer, we used GSEA analysis to predict the pathway associated with MAL2." (PMID 34567213, 2021). "MAL2 is frequently overexpressed in breast carcinoma, andMAL2 overexpression is associated with gain of thecorresponding locus at chromosome 8q24.12." (PMID 21423607, 2011). "The four-transmembrane MAL2 protein is frequently overexpressed in breast carcinoma, and MAL2 overexpression is associated with gain of the corresponding locus at chromosome 8q24.12." (PMID 20846453, 2010). "Accordingly, MAL2 has been included within a gene signature of poor prognosis in breast cancer, and MAL2 overexpression was associated with resistance to doxorubicin therapy in breast cancer patients." (PMID 19175940, 2009). "Since MAL2 is overexpressed in breast cancer, breast tumors might possibly be susceptible to treatment with ASBT-targeting nanomedicines." (PMID 37345137, 2023). "Thus, although NSMCE2 and MAL2 are highly expressed in Pan-Cancer tumors, their association to patients’ negative survival outcomes is specific to certain cancer types, including breast cancer." (PMID 36224576, 2022). "Cox regression models showed that high MAL2 expression could be an independent risk factor for breast cancer." (PMID 34567213, 2021). "Similarly, transmembrane protein Myelin and lymphocyte 2 (MAL2) that is frequently overexpressed in breast cancer associates with pMHC-I complexes to promote endocytosis and degradation; MAL2 knockdown improved tumor recognition and T-cell activation." (PMID 34201655, 2021). "Taken together, speculated high MAL2 expression might be associated with proliferation, metastasis, and prognosis of breast cancer by regulating the genes in these two gene sets." (PMID 34567213, 2021). "Given that our data shows that high NSMCE2 and MAL2 expression are associated with breast cancer patients’ poor survival outcomes, we next investigated if high levels of these markers could also be negatively associated with response to standard cancer therapies." (PMID 36224576, 2022). "Since we found that SEs are associated to NSMCE2 and MAL2 expression in breast tumors, we hypothesized that in breast cancer cells, expression of these genes should be reduced when disrupting the SE-enhancing function by blocking the binding of BRD4 to SEs with the inhibitors JQ1 or IBET151." (PMID 36224576, 2022). "Moreover, high MAL2 expression was associated with poor OS in patients with breast cancer." (PMID 34567213, 2021). "Dersh and Yewdell21 found that the MAL2 expression was associated with a poor prognosis for breast cancer, and its downregulation enhanced CD8+ T‐cell recognition of breast cancer in various experimental models." (PMID 40625454, 2024). "Breast cancer patients with low MAL2 had significantly longer overall survival (p = 0.0001) and disease-specific survival (p = 0.0026) than patients with high MAL2 expression." (PMID 38769215, 2024).
breast carcinoma (continued). "While the nature of the interactions between MAL2 signaling and breast cancer remains largely unexplored, recent studies have shed new light on its role in cancer immune escape." (PMID 38769215, 2024). "Surprisingly, we found that MUC1 is the binding protein of MAL2 in breast cancer cells by reviewing the literature." (PMID 36895039, 2023). "Increased MAL2 levels in breast cancer cell lines favored the formation of signaling complexes with the transmembrane tyrosine kinase receptor HER2 in membrane protrusions, contributing to the persistence of activated HER2 on the plasma membrane." (PMID 37345137, 2023). "We first explored the expression of MAL2 using Sangerbox tools and found that MAL2 expression was higher in breast cancer tissues than in normal tissues." (PMID 36895039, 2023). "MAL2 expression in breast cancer offers an example of protein function repurposing to favor cancer progression." (PMID 37345137, 2023). "Although its normal function is to transport proteins to the apical surface, overexpressed MAL2 in breast cancer cells promoted the endocytosis of tumor antigens via direct interaction with antigen-loaded MHC-I molecules." (PMID 37345137, 2023). "We found that MAL2 expression was higher in breast cancer tissues than in normal tissues and was related to poor prognosis in breast cancer patients." (PMID 36895039, 2023). "LncRNA LINC00460 blocks miR-320a to enhance the expression of myelin and lymphocyte protein 2 (MAL2), inhibiting ferroptosis in breast cancer." (PMID 37686142, 2023). "MAL2 expression levels are inversely correlated with infiltration levels of lymphocytes in the breast cancer microenvironment." (PMID 36895039, 2023). "Bioinformatics analysis and Immunohistochemical assay were applied to detect the correlation between MAL2 expression in breast cancer tissues and the prognosis of breast cancer patients." (PMID 37480012, 2023). "On a different study, Jeong and colleagues showed that MAL2 contributes to breast cancer by inducing accumulation of HER2 on the cell surface, thus enhancing oncogenic HER2 signaling." (PMID 36224576, 2022). "Through mining genomic datasets, we also found that NSMCE2 and MAL2 are frequently amplified in breast cancer patients and in breast cancer cell lines." (PMID 36224576, 2022). "These known tumor-promoting roles for NSMCE2 and MAL2 suggest that SE-driven overexpression of these two genes can support a variety of tumor-promoting processes in breast cancers cells." (PMID 36224576, 2022). "The prognostic value of MAL2 in breast cancer was assessed by the Kaplan–Meier method and Cox regression analysis." (PMID 34567213, 2021). "In the present study, we applied a comprehensive strategy to uncover the importance of MAL2 in breast cancer." (PMID 34567213, 2021). "In the multivariate model, stage, M classification, and MAL2 expression were significantly related to OS (all P < 0.05), especially high MAL2 expression, advanced breast cancer patients, and those with distant metastasis." (PMID 34567213, 2021). "Through yeast two-hybrid expression screening of a human breast cancer library, MAL2 was identified as the molecular chaperone of tumor protein D52-like protein (TPD52) and MUC1." (PMID 35111745, 2021). "Both the log-rank test and Cox proportional hazards model showed that the expression of MAL2 was significantly correlated with the prognosis of breast cancer." (PMID 34567213, 2021). "The MAL2 expression data of 1098 breast cancer samples and 113 adjacent controls were retrieved from the TCGA database." (PMID 34567213, 2021). "Gene set enrichment analysis (GSEA) was performed to identify the biological pathways correlated with MAL2 expression in breast cancer." (PMID 34567213, 2021). "In conclusion, our study showed MAL2 expression increased markedly in breast cancer patients and was related to overall survival." (PMID 34567213, 2021).
breast carcinoma (continued). "To assess further the MAL2 expression in breast cancer, we analyzed MAL2 across six public expressions, containing 10 analyses from the Oncomine database." (PMID 34567213, 2021). "MAL2 was also proved to promote immune evasion by suppressing tumor antigen presentation in breast cancer." (PMID 34567213, 2021). "Kaplan–Meier curves with the log-rank test were applied to explore the prognostic value of MAL2 expression and the overall breast cancer survival rate." (PMID 34567213, 2021). "In conclusion, both in the Kaplan–Meier model and the Cox proportional hazard regression model, the results indicated that MAL2 expression in breast cancer was significantly correlated with the prognosis of patients." (PMID 34567213, 2021). "The univariate Cox proportional hazards model showed that MAL2 expression, stage, T classification, N classification, and M classification of breast cancer patients were significantly correlated with the prognosis of patients." (PMID 34567213, 2021). "Both bioinformatics and RT-qPCR results showed that MAL2 was expressed at high levels in breast cancer tissues compared with the adjacent tissues." (PMID 34567213, 2021). "Here, we conducted this study to consider further the significance of MAL2 expression in the prognosis of breast cancer." (PMID 34567213, 2021). "To certify the difference in MAL2 expression in the TCGA data set, we performed RT-qPCR to detect the expression of MAL2 in 32 pairs of breast cancer tissues (including 32 tumor tissues and 32 adjacent tissues)." (PMID 34567213, 2021). "MAL2 was upregulated significantly in breast cancer based on the results of the Oncomine and TCGA database analyses." (PMID 34567213, 2021). "MAL2 also showed a broad cytoplasmic distribution in renal cell carcinomas and in breast carcinomas and cell lines." (PMID 20846453, 2010). "Increased MAL2 expression has been validated in other cancer types using RT-PCR, and demonstrated at the protein level in renal cell and breast carcinomas." (PMID 20846453, 2010). "The intracellular localisation of MAL2 in breast cancer cells was determined using indirect immunofluorescence and confocal microscopy, and compared with that of MUC1." (PMID 19175940, 2009). "MAL2 was first identified through its expression in breast carcinoma and interactions with D52-like proteins within the Y2H system." (PMID 19175940, 2009). "Rabbit MAL2 antisera were employed in Western blot analyses of total protein extracts from a panel of human breast carcinoma cell lines, as well as MCF-10A breast epithelial cells." (PMID 19175940, 2009). "The initial identification of MAL2 suggested its overexpression in breast cancer, which is supported by the MAL2 gene being found at chromosome 8q24, which is frequently gained in breast and other cancers." (PMID 19175940, 2009). "MAL2 was identified as a partner for tumor protein D52-like proteins through yeast two-hybrid (Y2H) expression screening of a human breast carcinoma library." (PMID 19175940, 2009). "MAL2 is overexpressed in breast cancer, and its high expression correlates with poor prognosis." (PMID 38769215, 2024). "This study aimed to investigate the role of MAL2 in breast cancer (BC)." (PMID 37480012, 2023). "We therefore performed rescue experiments using the β-catenin agonist SKL2001 to investigate whether MAL2 regulates the invasion and metastasis of breast cancer cells via the β-catenin/c-Myc axis." (PMID 37480012, 2023). "MAL2 also promotes breast cancer cell proliferation, migration, and invasion by regulating the EMT." (PMID 36895039, 2023). "The scrutiny of the two sources of information, datasets and published studies, reveals potential prognostic applications of MAL-family members as cancer biomarkers—for instance, MAL2 in breast cancer, MAL2 and MALL in pancreatic cancer, and MAL and MYADM in lung cancer—and other biomedical uses." (PMID 37345137, 2023).
breast carcinoma (continued). "Additionally, MAL2 has also been reported to enhance resistance to trastuzumab in breast cancer cells by stabilizing HER2." (PMID 37958451, 2023). "Besides, it was also found that MAL2 can promote the proliferation, invasion, and metastasis of breast cancer cells via the EMT pathway." (PMID 36895039, 2023). "The role of MAL2 in these processes in breast cancer should therefore be carefully re-evaluated." (PMID 37345137, 2023). "Several studies have identified MAL2 amplification and/or overexpression in breast cancer and in other cancer types including primary ovarian carcinoma, pancreatic carcinoma, prostate adenocarcinoma, oral squamous cell carcinoma and head and neck squamous cell carcinoma." (PMID 35437691, 2022). "Thus, frequent copy number gains of the NSMCE2 and MAL2 loci in breast cancer suggest that higher gene expression levels for these genes indeed contribute to tumor progression." (PMID 36224576, 2022). "On the METABRIC dataset, high expression of MAL2 significantly associates with worse overall survival of breast cancer patients, while high NSMCE2 follows the same trend without reaching statistical significance." (PMID 36224576, 2022). "The MAL2 protein has now been known to interact with the MHC-I complex and endosome-associated RAB proteins to inhibit the presentation of MHC-I molecules on cell membrane to drive immune evasion in breast cancer." (PMID 35437691, 2022). "This study aimed to explore the prognostic significance of MAL2 in breast cancer." (PMID 34567213, 2021). "As a result, MAL2 was found to significantly upregulate in breast carcinoma tissues." (PMID 34567213, 2021). "Besides, a single-sample GSEA (ssGSEA) was used to assess the relationship between the level of immune infiltration and MAL2 in breast cancer." (PMID 34567213, 2021). "However, further studies are warranted to verify the value of MAL2 in breast cancer prognosis evaluation." (PMID 34567213, 2021). "MAL2 expression may be an independent predictor of a poor disease survival prognosis in breast cancer patients." (PMID 34567213, 2021). "Overexpression of MAL2 correlates with poor prognosis and lower immune infiltrating levels of eosinophils and plasmacytoid dendritic cells in breast cancer and may become a biomarker for breast cancer prognosis." (PMID 34567213, 2021). "Furthermore, the RT-qPCR outcome verified the high expression of MAL2 in breast cancer, which coincides with the results of the bioinformatics assay and previous studies in other tumors." (PMID 34567213, 2021). "As for breast cancer, previous studies showed that MAL2 could induce proliferation and invasion of breast cancer cell lines by adjusting the epithelial-mesenchymal transition." (PMID 34567213, 2021). "Moreover, high MAL2 expression correlates with reduced immune infiltration of eosinophils and plasmacytoid dendritic cells in breast cancer." (PMID 34567213, 2021). "Besides, the MAL2 expression level negatively correlated with infiltrating levels of eosinophils and plasmacytoid dendritic cells in breast cancer." (PMID 34567213, 2021). "MAL2 expression has been shown to be elevated by independent expression microarray studies in ovarian cancer and increased at RNA and protein levels in renal cell and breast cancers." (PMID 28562687, 2017). "Despite numerous reports of MAL2 overexpression in breast cancer, little is known about how increased MAL2 expression may provide an advantage to cancer cells." (PMID 19175940, 2009). "Several studies have now identified MAL2 amplification and/or overexpression in breast cancer." (PMID 19175940, 2009). "Additionally, MAL2 has been found to be an independent prognostic predictor of breast cancer." (PMID 36895039, 2023). "The associations of the Panel 2 markers MAL2, EMP2, CCNE2 and HJURP with short OS may point to different biological characteristics of the enriched cells and warrant further studies in aggressive breast cancer subtypes." (PMID 36831613, 2023).